SCARF1 (scavenger receptor class F member 1)
Diseases named in the same sentence as SCARF1 in open-access papers:
SCARF1 is named in the same sentence as 32 diseases in open-access papers, as found by Europe PMC text mining. Sharing a sentence is not in itself a finding about the gene and the disease. The quoted sentences say what the papers report.
Autoimmunity (6 papers, 2014 to 2022). The occurrence of an immune reaction against the organism's own cells or tissues. "SCARF1 has been shown to play a key role in the prevention of autoimmunity, as SCARF1-deficient mice spontaneously develop systemic lupus erythematosus (SLE) due to the severely impaired clearance of apoptotic cells in the spleen." (PMID 30631321, 2018). "SCARF1 mediates the clearance of apoptotic cells and prevents autoimmunity." (PMID 35962453, 2022). "As most of the cell surface receptors present SCARF-1, it has the potential to be utilized in cell/cell membrane-based applications, such as modulating SLE autoimmunity, delivering payloads to atherosclerotic lesions by targeting LDL, and apoptotic cell imaging in vivo via C1q-PS binding features." (PMID 33796822, 2020). "Shedding light on the SCARF-1 pathway not only reveals its fundamental role in physiology, but also, this new SCARF-1 pathway can be used in new research directions for various diseases, including autoimmune disorders." (PMID 33796822, 2020). "Presently, the answer is still not clear, although of the major PS recognition receptors that give rise to autoimmunity in mice (Mer, Tim-1, Tim-4, SCARF1, and CD300f), their involvement in human autoimmunity is not yet obvious from genetic linkage analysis." (PMID 25426118, 2014).
hepatocellular carcinoma (5 papers, 2017 to 2024). A malignant tumor that arises from hepatocytes. "Recent data also show that SCARF1 is down-regulated in hepatocellular carcinoma and loss of SCARF1 is associated with poorly differentiated tumors." (PMID 39541158, 2024). "Higher SCARF1 expression in hepatocellular carcinoma tumor tissues was highly prognostic of better OS, DFS and PFS." (PMID 35962453, 2022). "SCARF-1 was also present in the sinusoids of hepatocellular carcinoma (HCC) tissue and was observed in tumour-associated and capsule-associated vessels, all of which are important sites for lymphocyte trafficking in HCC." (PMID 29242513, 2017). "In this study, we describe SCARF-1 expression in the sinusoids and major vessels of the normal human liver and within fibrotic septa of chronic liver diseases and the peritumoral stroma of hepatocellular carcinoma (HCC)." (PMID 29242513, 2017). "However, the contribution of SCARF1 to hepatocellular carcinoma (HCC) is currently unknown." (PMID 34354939, 2020).
systemic lupus erythematosus (5 papers, 2018 to 2024). An autoimmune multi-organ disease typically associated with vasculopathy and autoantibody production. "Over the past decades, SCARF1 has been linked to a number of diseases, including cardiovascular diseases, systemic lupus erythematosus, fungal keratitis, and cancer." (PMID 39541158, 2024). "The importance of SCARF1 in immunological processes was demonstrated using a SCARF1-deficient mice model, which developed systemic lupus erythematosus-like autoimmune disease." (PMID 36291675, 2022). "SCARF-1−/− mice were predisposed to systemic lupus erythematosus (SLE) and autoimmune nephritis due to an increase in circulating autoantibodies." (PMID 34065321, 2021). "SCARF1-knockout mice can develop symptoms similar to systemic lupus erythematosus disease and lead to accumulation of apoptotic cells in the immune organs, suggesting that it is involved in the removal of apoptotic cells and maintaining homeostasis." (PMID 39541158, 2024). "Unlike most scavenger receptors, SCARF1 is an essential protein, as SCARF1-deficient mice exhibit a severe resting phenotype in which they develop systemic lupus erythematosus (SLE)-like disease, thus highlighting the importance of SCARF1-mediated clearance of apoptotic host cells in homeostasis." (PMID 29725698, 2018).
atherosclerosis (4 papers, 2015 to 2026). A disease characterized by the build-up of fatty material and calcium deposition in the arterial wall resulting in partial or complete occlusion of the arterial lumen. "SCARF1 may also associate with the extravasation of leukocytes from circulation into inflamed tissues during injury or infection, thus having a role in the inflammatory changes in vessel walls and the initiation of atherosclerosis." (PMID 39541158, 2024). "Utilizing bulk RNA sequencing, six core efferocytosis-related genes (STAB1, ANO5, GULP1, LGR6, SCARF1, and CAMK2G) were identified, which exhibit significant diagnostic potential in atherosclerosis." (PMID 42272635, 2026). "SCARF1 plays a crucial role in atherosclerosis, endothelial injury/dysfunction, inflammation, and host innate immunity, predominantly binding to carbamylated LDLs with its proatherogenic effect on human endothelial cells." (PMID 30823506, 2019).
liver cancer (2 papers, 2017 to 2020). An epithelial or non-epithelial malignant neoplasm that arises from the liver. "C3orf14 has been shown to be differentially methylated in cervical and prostate cancer while CDR2L and SCARF1 have been proposed to mediate immune response in ovarian and liver cancer, respectively." (PMID 33087122, 2020). "The fact that SCARF-1 is down-regulated in liver cancers, particularly those that are poorly differentiated and thus have the worst prognosis, also suggests it may play a role in tumour immune control through recruitment of inflammatory cells in response to microenvironmental signals." (PMID 29242513, 2017).
colon adenocarcinoma (1 paper, 2020). "In addition, SCARF1 expression is also reduced in tumor tissues of other gastrointestinal cancers, namely esophageal carcinoma, stomach adenocarcinoma and colon adenocarcinoma, compared to their respective non-tumorous tissue controls." (PMID 34354939, 2020).
colonic cancers (1 paper, 2020). "Down regulation of SCARF1 was associated with a poorer outcome and interestingly this may be a relevant to other tumors as we showed that tumors of other gastrointestinal cancers, such as esophageal, gastric and colonic cancers, also significantly down-regulated SCARF1 expression." (PMID 34354939, 2020).
End Stage Liver Disease (1 paper, 2017). Final stage of a liver disease when the liver failure is irreversible and LIVER TRANSPLANTATION is needed. "Having observed elevated levels of SCARF-1 in end-stage liver disease, we investigated whether SCARF-1 was also expressed in the tumour environment." (PMID 29242513, 2017).
glioblastoma (1 paper, 2020). The most malignant astrocytic tumor (WHO grade IV). "In addition to changes in Mmps, we also found that glioblastoma was associated with an increased expression of mRNAs encoding microglial phagocytic receptors—Cd93, Msr1, Cd36, Olr1, Megf10, Clec7a, and Scarf1." (PMID 32299465, 2020).
inflammatory liver diseases (1 paper, 2017). "SCARF-1 was strongly expressed on hepatic sinusoids and vessels, primary sites of lymphocyte recruitment during inflammatory liver diseases and a 60 kDa form of the protein was present in chronic liver disease samples, but absent from normal pathological control tissue." (PMID 29242513, 2017).
metastatic disease (1 paper, 2020). "Next, we explored the SCARF1 expression levels in cases of HCC at different stages of the disease, from early stage disease (Stage I) through to highly developed and metastatic disease (Stage IV)." (PMID 34354939, 2020).
pancreatic adenocarcinoma (1 paper, 2020). "In contrast to other GI malignancies, we found that pancreatic adenocarcinoma tumor tissues exhibited comparable SCARF1 expression to non-tumorous tissues." (PMID 34354939, 2020). "Interestingly, and in contrast to the other cancer types explored here, pancreatic adenocarcinoma tumors showed no dysregulation of SCARF1 expression when compared to non-tumorous tissues." (PMID 34354939, 2020).
Stroke (1 paper, 2022). Sudden impairment of blood flow to a part of the brain due to occlusion or rupture of an artery to the brain. "In blood, we identified 5 genes (MMP12, SCARF1, ABO, F11, and CKAP2) that had causal relationships with stroke and stroke subtypes." (PMID 35449099, 2022). "Furthermore, 5 different genes (MMP12, ABO, SCARF1, F11, and CKAP2) were discovered in blood, which indicated two distinct pathogenesis for stroke in brain and blood." (PMID 35449099, 2022).
tumor (8 papers, 2015 to 2023). "SCARF1 within HCC was largely associated with tumor endothelial cells and adhesion studies suggested that it played a role in the specific recruitment of proinflammatory CD4+ T cells (CD4+CD25−) to HCC tumor tissues." (PMID 34354939, 2020). "Next, via a combination of TGCA data analysis and immunofluorescent staining, we determined that SCARF1 within HCC was largely associated with tumor endothelial cells." (PMID 34354939, 2020). "We further aimed to confirm these findings by correlating SCARF1 expression with other parameters commonly associated with increased tumor aggressiveness and grade, in particular, we focussed on Aneuploidy Score and Buffa Hypoxia Score." (PMID 34354939, 2020). "For example, the uptake of these factors by SCARF1 could prevent neutrophil and macrophage accumulation in the tumor microenvironment, thus providing an alternative mode-of-action for the anti-tumoral action of SCARF1, as myeloid cell accumulation is often associated with poor prognosis in HCC." (PMID 34354939, 2020). "Consequently, we found an association with loss of SCARF1 expression with aggressive tumor biology." (PMID 34354939, 2020). "A number of the top 25 genes commonly regulated in conjunction with SCARF1 within HCC tumor tissues were endothelial-specific and all demonstrated a strong positive correlation with levels of SCARF1 expression." (PMID 34354939, 2020). "In support of the pathological findings, high SCARF1 expression in HCC tumor tissues was found to correlate with a better overall survival, disease-free survival and progression-free survival." (PMID 34354939, 2020). "To explore the cell-specific expression of SCARF1 within HCC tumors, we correlated the gene expression of the scavenger receptor superfamily with a number of gene sets known to be expressed in tumor-associated cell populations." (PMID 34354939, 2020). "We corroborated these findings with immunohistochemical staining, which also showed reduced protein expression in HCC tumor tissues, and next explored the relationship of SCARF1 expression with tumor progression." (PMID 34354939, 2020). "Differentiation status of solid tumors informs their histological grading and, consequently, gives an indication of tumor aggressiveness; therefore, we initially explored the expression of SCARF1 in HCC tumors of different histological grades." (PMID 34354939, 2020). "Next, to corroborate the expression of SCARF1 in tumor sinusoidal endothelial cells we undertook dual immunofluorescence staining of SCARF1 and CD31, a commonly used tumor endothelial marker known to be expressed in HCC." (PMID 34354939, 2020). "SCARF-1 mRNA levels in HCC tumour tissue also demonstrated a trend for down-regulation, compared to normal liver tissue." (PMID 29242513, 2017). "We detected SCARF-1 in HCC at different stages of differentiation in which the protein and was mainly associated with tumour sinusoids and tumour-associated vessels and within the tumour margin and on capsule-associated vessels." (PMID 29242513, 2017). "SREC-I/SCARF1 was able to bind to Hsp70 and Hsp90 in DC and mediated cross-presentation of associated tumor antigens, leading to activated CTL." (PMID 27199984, 2016). "Tumor-associated myeloid cells exhibited higher transcriptional expression of molecules linked to the “find me” (G2A), “eat me” (CD93, TIM1, SCARF1, SLC2A1, GAS6, TREM2, AXL, C1QA), and downstream processing (NR1H3, ATG7, PPARG, ABCA1, PPARD, DOCK180) phases of efferocytosis." (PMID 36439171, 2022). "Our findings also suggest that future agonistic agents acting to increase the expression of SCARF1 within tumors could boost the numbers of tumor-infiltrating proinflammatory lymphocytes." (PMID 34354939, 2020). "Within HCC tumor tissue, we demonstrated a strong co-localization of SCARF1 and CD31." (PMID 34354939, 2020).
tumor (continued). "Previously, we have shown that the level of immunohistochemical staining of SCARF1 in poorly differentiated HCC tumor tissues was greatly reduced when compared with well- and moderately-differentiated tumors; here, we aimed to utilize the TGCA dataset to further corroborate those findings." (PMID 34354939, 2020). "Utilizing qPCR analysis, we have previously shown a strong trend for decreased SCARF1 mRNA expression in HCC tumor tissue compared to normal liver tissue; here, we corroborated this finding with publically-available RNA-sequencing data from The Cancer Genome Atlas (TGCA)." (PMID 34354939, 2020). "In both instances, SCARF1 expression demonstrated a moderate negative correlation in HCC tumor tissues, thus providing further evidence that a loss of SCARF1 expression is associated with adverse biology and aggressive HCC tumors." (PMID 34354939, 2020). "Consistent with our previous findings in normal and chronically diseased liver tissues, SCARF1 in HCC tumor tissues exhibited a highly sinusoidal expression pattern and correlation data from the TGCA dataset further corroborated its largely endothelial expression." (PMID 34354939, 2020). "To assess if SCARF1 could functionally contribute to the balance of immune effector vs. immunosuppressive subsets within the tumor microenvironment, we studied its role in CD4+ T cell subset recruitment." (PMID 34354939, 2020). "Additionally, higher SCARF1 expression in HCC tumor tissues was highly prognostic of better overall, disease-free and progression-free survival." (PMID 34354939, 2020). "Interestingly, with the exception of ASGR1, which is expressed in HCC tumor cells and known to prevent metastasis, SCARF1 was the only other scavenger receptor gene which was associated with increased survival in HCC." (PMID 34354939, 2020). "The correlation of SCARF1 with CD4+ T cell tumor infiltration and its role in recruitment may help in the identification of patients who will respond to immunotherapies." (PMID 34354939, 2020). "Interestingly, of the entire scavenger receptor superfamily, SCARF1 demonstrated the most endothelial-specific signature within HCC tumor tissues, exhibiting low to moderate correlations with the majority of the other cell type gene sets." (PMID 34354939, 2020). "SCARF1 expression was downregulated in HCC tumor tissues, compared to non-tumoral tissues, and loss of SCARF1 expression was associated with poorly differentiated/aggressive tumors." (PMID 34354939, 2020). "SCARF1 has been shown to bind a range of endogenous ligands, such as oxidized lipoproteins, heat shock proteins and apoptotic cells, and regulate LPS responses; therefore, all these functions could also potentially influence the tumor microenvironment." (PMID 34354939, 2020). "Furthermore, SCARF1 expression could potentially be targeted to alter the inflammatory status of the tumor microenvironment, shifting it toward an anti-tumoral immune response and supporting immunotherapy regimes for HCC." (PMID 34354939, 2020). "Endothelial SCARF1 expression in tumor biopsies may provide critical prognostic information." (PMID 34354939, 2020). "Additionally, SCARF1 may also be a novel endothelial target that could help re-programme the microenvironment of HCC by promoting effector T cell tumor infiltration." (PMID 34354939, 2020). "Surface area quantification of SCARF1 staining in matched samples from several patients showed a significant (p ≤ 0.01) reduction in SCARF1 expression in tumor tissues, when compared to distal, non-tumorous tissues." (PMID 34354939, 2020). "Analysis of the TGCA data showed that SCARF1 expression is significantly (p ≤ 0.001) lower in HCC tumor tissues in comparison to non-tumorous tissues." (PMID 34354939, 2020). "Having previously shown that SCARF1 mediates the specific recruitment of CD4+ T cells to LSEC in inflammatory conditions, we next explored whether it could play a role in the recruitment of TILs to the HCC tumor microenvironment." (PMID 34354939, 2020).
tumor (continued). "Having previously shown that SCARF1 mediates the specific recruitment of CD4+ T cells to LSEC in vitro, under conditions of physiological flow, we aimed to determine whether it could play a role in the recruitment of TILs to the HCC tumor microenvironment." (PMID 34354939, 2020). "Using TIMER, we confirmed that SCARF1 expression is absent from tumor cells, as indicated by a negative “purity” correlation (−0.295), and demonstrated a moderate positive correlation with CD4+ T cell infiltration (purity-corrected partial Spearman's rho value = 0.420, p = 3.79e−16)." (PMID 34354939, 2020). "Therefore, an active downregulation of SCARF1 expression, in order to provide more favorable tumorigenic conditions, may not play a role in the pathogenesis of this tumor." (PMID 34354939, 2020). "In addition to high SCARF1 expression correlating with a good outcome, our functional assays also suggest that SCARF1 may have an active anti-tumoral role for by promoting the recruitment of effector CD4+ T cells rather than tumor promoting regulatory T cells (Tregs)." (PMID 34354939, 2020).
infection (7 papers, 2013 to 2024). The state of being infected such as from the introduction of a foreign agent such as serum, vaccine, antigenic substance or organism. "Two studies have implicated SCARF1 in adherence of bacteria on epithelial tissues and have suggested that the bacteria may utilise the scavenger receptor to promote their dissemination from the primary infection site to systemic circulation and distal tissues." (PMID 29725698, 2018). "The few proteins for which a fold-change >2 or <−2 was observed 48 h after infection are involved in apoptosis (SCARF1, PLSCR3), ubiquitination (UBE2E3, OTULIN), or the response to type I IFN (OAS2)." (PMID 35337059, 2022). "Scarf1 mRNA was present only in the endothelium both before and 6h to 2d after infection." (PMID 36092940, 2022).
cancer (4 papers, 2020 to 2024). A tumor composed of atypical neoplastic, often pleomorphic cells that invade other tissues. "When examining the top 100 gene pairs, BSDC1, C3orf14, CDR2L, LRRC42, MEOX2, NRG2, and PLEKHA6, and SCARF1 were consistently identified by feature selection methods to be associated with cancer status." (PMID 33087122, 2020). "C3orf14, CDR2L, LRRC42, MEOX2, NRG2, and SCARF1 have been previously associated with cancer." (PMID 33087122, 2020). "In contrast to this, we show that higher intratumoral expression of SCARF1 in HCC was associated with less advanced and less aggressive cancers." (PMID 34354939, 2020). "Furthermore, expression of SCARF1 showed no prognostic value with regards to cancer staging or in the presence/absence of vascular invasion." (PMID 34354939, 2020). "Interestingly, C3orf14, CDR2L, LRRC42, MEOX2, NRG2, and SCARF1 are known carcinogenic genes, while BSDC1 and PLEKHA6 have not been described in previous cancer literature." (PMID 33087122, 2020).
gastrointestinal tumors (1 paper, 2020). "Further experimental studies of SCARF1 could therefore lead to novel combination immunotherapeutic strategies in HCC as well as in other gastrointestinal tumors." (PMID 34354939, 2020).
SCARF1 also shares sentences with these, for which no sentence is quoted: autoimmune disease (3 papers); cardiovascular diseases (2); bacterial infection (1); brain injury (1); Cognitive impairment (1); Diabetes (1); epilepsy (1); esophageal carcinoma (1); fungal infection (1); fungal keratitis (1); Intellectual disability (1); Miller-Dieker syndrome (1); Obesity (1); prostate carcinoma (1); stomach adenocarcinoma (1).